LNCAROD (lncRNA activating regulator of DKK1)
Synonyms: lnc-MBL2-4; A-ROD; LOC105378305; formerly LINC01468
Gene: Long non-coding RNA gene on chromosome 10 (52,445,975 to 52,755,570, reverse strand). Ensembl gene ENSG00000231131.
Diseases named in the same sentence as LNCAROD in open-access papers:
LNCAROD is named in the same sentence as 16 diseases in open-access papers, as found by Europe PMC text mining. Sharing a sentence is not in itself a finding about the gene and the disease. The quoted sentences say what the papers report.
head and neck squamous cell carcinoma (10 papers, 2020 to 2024). A squamous cell carcinoma that arises from any of the following anatomic sites: lip and oral cavity, nasal cavity, paranasal sinuses, pharynx, larynx, and salivary glands. "LNCAROD, an oncogenic lncRNA, displays differential expression between head and neck squamous cell carcinoma (HNSCC) and normal samples, and the overexpression of LNCAROD is linked to the advanced T stage and poor overall survival of HNSCC." (PMID 35534472, 2022). "Also, in an interesting study, the authors have revealed that LNCAROD overexpressed in head and neck squamous cell carcinoma (HNSCC) is associated with tumor progression, proliferation, migration, advanced T stage and poor overall survival." (PMID 38075202, 2024). "As a newly identified lncRNA, LNCAROD has been reported as an oncogene in gastric cancer and head and neck squamous cell carcinoma." (PMID 39367700, 2024). "METTL3‐mediated and METTL14‐mediated m6A modification enhances the stability of LNCAROD in head and neck squamous cell carcinoma (HNSCC) cells, an effect that is associated with the high expression of LNCAROD in HNSCC." (PMID 34432955, 2021). "Overexpression of LNCAROD related to m6A methylation took part in malignant development of head and neck squamous cell carcinoma through facilitating YBX1–HSPA1A interaction." (PMID 34277627, 2021). "Similarly, LNCAROD is up-regulated by METTL3/METTL14 in head and neck squamous cell carcinoma (HNSCC) and impels its tumorigenicity through preventing YBX1 from degradation." (PMID 33754077, 2021). "METTL3/METTL14-induced m6A methylation stabilized LNCAROD in head and neck squamous cell carcinoma (HNSCC) tissue, which augmented malignant cell multiplication and invasion in vivo and in vitro." (PMID 36553003, 2022). "Likewise, METTL3- and METTL14-mediated m6A modification of LncAROD enhanced its stability and promoted ternary complex formation with HSPA1A and YBX1, driving progression in head and neck squamous cell carcinoma." (PMID 34458149, 2021).
bladder urothelial carcinoma (1 paper, 2020). "LNCAROD is also highly expressed in bladder urothelial carcinoma and predicts unfavorable prognosis, suggesting an oncogenic role in cancer development." (PMID 32216017, 2020).
liver cancer (1 paper, 2024). An epithelial or non-epithelial malignant neoplasm that arises from the liver. "For example, the splicing factor SRSF3 can directly bind to LNCAROD, inducing PKM isoform switching to PKM2 and enhancing aerobic glycolysis in liver cancer cells, promoting tumor malignancy and chemotherapy resistance." (PMID 38785569, 2024).
ovarian carcinoma (1 paper, 2023). A malignant neoplasm originating from the surface ovarian epithelium. "The association between MROCK1 and LNCAROD and survival and prognosis should be validated in ovarian cancer patients." (PMID 37597098, 2023). "Both MROCKI and LNCAROD act as protective factors in ovarian cancer patients because higher expression of MROCKI and LNCAROD in tumor tissues are associated with the higher survival rate." (PMID 37597098, 2023). "In our study, LNCAROD is a protective factor, where the higher expression of LNCAROD in ovarian cancer patients have a higher survival rate." (PMID 37597098, 2023). "In vitro experiments are required to determine the functions of MROCK1 and LNCAROD in ovarian cancer cells." (PMID 37597098, 2023). "Whereas the function of LNCAROD has been studied in other cancers, the function of MROCKI and AC096667.1 remains largely unknown, especially in pyroptosis and ovarian cancer." (PMID 37597098, 2023).
tumor (7 papers, 2018 to 2024). "In this study, we unveiled the tumor promotive function of LNCAROD in HNSCC development." (PMID 32216017, 2020).
LNCAROD also shares sentences with these, for which no sentence is quoted: cancer (4 papers); infection (2); endometrial cancer (1); esophageal squamous cell carcinoma (1); gastric cancer (1); hepatocellular carcinoma (1); lung adenocarcinoma (1); lung carcinoma (1); Stroke (1); typhoid fever (1); viral infection (1).